GDF15 (growth differentiation factor 15)
Diseases named in the same sentence as GDF15 in open-access papers (continued):
Sharing a sentence is not in itself a finding about the gene and the disease.
nosocomial infection (1 paper, 2021). An infection acquired in a hospital or other healthcare setting. "We recently identified GDF-15 as a circulating factor after severe injury that is associated with NK cell suppression early after injury and with an enhanced risk for nosocomial infections." (PMID 35054405, 2021).
ocular hypertension (1 paper, 2022). Abnormally high intraocular pressure. "The findings of this study reveal elevated levels of GDF15 in the AH, as well as the serum, of POAG patients, indicating the plausible role for GDF15 in the pathobiology of ocular hypertension." (PMID 35160195, 2022).
organic acidemia (1 paper, 2025). "From this perspective, markers of mitochondrial dysfunction, such as fibroblast growth factor 21 (FGF-21) and growth differentiation factor 15 (GDF-15), could be promising prognostic indicators of organic acidemia complications associated with mitochondrial dysfunction." (PMID 41399536, 2025).
Osteopenia (1 paper, 2022). Osteopenia is a term to define bone density that is not normal but also not as low as osteoporosis. "The findings of this study indicate that GDF-15 may be a target for future therapeutics for sarco-osteopenia and, eventually, for recovery and longevity." (PMID 36325442, 2022).
osteosclerosis (1 paper, 2015). Abnormally high bone density. "Therefore, in advanced (fibrotic and ostesclerotic) stages, GDF15 may contribute to the development of BM fibrosis and osteosclerosis by accelerating the growth of fibroblasts and promoting the osteoblastic differentiation of BM-MSCs." (PMID 26276681, 2015). "Because osteosclerosis is another characteristic feature of PMF and osteoblasts are derived from BM-MSCs, we next investigated the effects of GDF15 on the proliferation and differentiation of human BM-MSCs." (PMID 26276681, 2015).
primary myelofibrosis (1 paper, 2015). Myelofibrosis with myeloid metaplasia is a myeloproliferative disease with annual incidence of approximately 1 case per 100,000 individuals and age at diagnosis around 60 (an increased prevalence is noted in Ashkenazi Jews). "We found that serum GDF15 levels were elevated in almost all these patients, particularly in patients with primary myelofibrosis (PMF)." (PMID 26276681, 2015). "We found that patients with primary myelofibrosis (PMF) showed very high serum GDF15 levels, which prompted us to further investigate the source of GDF15 in the BM, and to assess the contribution of GDF15 to the pathogenesis of PMF." (PMID 26276681, 2015).
psychosis (1 paper, 2017). "Higher CGI scores (more severe psychosis) were associated with lower GDF15 levels (βstandardized = −0.221, t = −2.58, p = 0.012)." (PMID 28801589, 2017). "Association between GDF15 levels and severity of psychotic illness was assessed within the psychosis group through the severity score CGI." (PMID 28801589, 2017). "Higher CGI, an indication of more severe psychosis, was associated with lower GDF15 levels (βstandardized = −0.188, t = −2.55, p = 0.012)." (PMID 28801589, 2017). "Within the patient cohort GDF15 levels were evaluated for association with age, gender, lifestyle factors, C-reactive protein levels, psychosis severity and metabolic disorder." (PMID 28801589, 2017). "We hypothesized that plasma GDF15 levels would be (i) increased in psychosis, (ii) elevated by metabolic comorbidity, (iii) associated with CRP levels in patients." (PMID 28801589, 2017). "The aims of the present study were to determine if plasma GDF15 levels (i) were different in psychosis patients compared to healthy controls, (ii) associated with severity of psychotic illness, and (iii) associated with degree of metabolic comorbidity and CRP levels in the patients." (PMID 28801589, 2017). "Our finding that GDF15 levels were lower in the more severely afflicted psychosis patients could reflect the loss of anti-inflammatory and neuroprotective capabilities in these patients." (PMID 28801589, 2017). "In the present study, we show for the first time that GDF15 is elevated in plasma of psychosis patients when compared to healthy age and gender matched controls." (PMID 28801589, 2017). "Within the psychosis cohort, GDF15 levels, when corrected for age, metabolic health and lifestyle factors, were negatively correlated with psychosis severity (β = −0.218, p = 0.012)." (PMID 28801589, 2017). "To conclude, we report that plasma GDF15 levels are elevated in chronic psychosis patients compared to healthy controls, and that the GDF15 levels are negatively correlated with psychosis severity." (PMID 28801589, 2017). "Psychosis patients had significantly higher plasma GDF15 levels compared to healthy controls: medianpatients = 744 ng/mL, mediancontrols = 516 ng/mL, p < 0.001." (PMID 28801589, 2017). "Study replication in larger cohorts will be necessary to assess the potential of GDF15 as a prognostic biomarker in psychosis." (PMID 28801589, 2017). "In the present study we measured GDF15 levels in plasma of 120 psychosis patients compared to 120 age and gender matched healthy controls." (PMID 28801589, 2017). "Psychosis patients had elevated GDF15 levels compared to controls (medianPsychosis = 744 ng/mL, mediancontrols = 516 ng/mL, p < 0.001)." (PMID 28801589, 2017). "In the psychosis group and healthy controls, the GDF15 plasma levels were significantly correlated with age at sampling." (PMID 28801589, 2017). "A final model was created to compare metabolic effects with lifestyle, demographic and psychosis severity factors in their contribution to GDF15 level variance." (PMID 28801589, 2017). "While GDF15 levels were elevated in patients versus healthy controls, the negative correlation between psychosis severity and GDF15 suggests a loss of anti-inflammatory GDF15 mediated functionality in severe psychosis." (PMID 28801589, 2017). "A plausible explanation for this could be that GDF15 is anti-inflammatory and thus higher levels of GDF15 could contribute to milder psychosis related co-morbidity and improved outcomes." (PMID 28801589, 2017). "However, in our cohort the metabolic factors were relatively less important than the psychosis severity index in explaining GDF15 levels." (PMID 28801589, 2017). "In addition, we show in our psychosis patient cohort, that GDF15 levels are lower in patients with a more severe psychosis." (PMID 28801589, 2017).
psychosis (continued). "In order to be able to propose GDF15 as a potential prognosis biomarker in psychosis, further studies delineating the role of GDF15 in CNS pathways, especially where they intersect with the pathogenesis of psychosis, are required." (PMID 28801589, 2017). "While in this study we have analyzed patient plasma for GDF15 and correlated this with psychosis severity, analyzing the CSF could prove to be a more attractive biological sample for the purpose of understanding the role of GDF15 in psychosis." (PMID 28801589, 2017). "Therefore, we have investigated GDF15 in the context of psychotic disorders with a focus on relating the GDF15 levels to psychosis severity." (PMID 28801589, 2017). "An assessment of plasma GDF15 levels in relation to psychosis has not previously been reported, thus our findings warrant replication efforts as well as an investigation of GDF15 levels as a prognostic marker for psychosis." (PMID 28801589, 2017). "Some patients with BD, especially BD type I, have episodes of psychosis, but GDF15 levels have not previously been studied specifically in relation to psychosis." (PMID 28801589, 2017). "However, psychosis severity was not investigated in relation to plasma GDF15 levels." (PMID 28801589, 2017). "In the present study we did not detect a significant correlation between GDF15 levels and CRP levels within the psychosis patients." (PMID 28801589, 2017).
pulmonary edema (1 paper, 2022). Accumulation of fluid in the lung tissues causing disturbance of the gas exchange that may lead to respiratory failure. "Additionally, GDF-15 exhibited direct and strong correlations not only with clinical aspects suggestive of acute HF (e.g., pulmonary crackles, pulmonary edema) but also with certain predictors of a poor outcome, such as the need for inotropic support, lactate level, or length of hospitalization." (PMID 36556311, 2022).
pulmonary TB (1 paper, 2021). "When only the individuals with pulmonary TB were compared to those with ORD, significant differences were observed for SAA, CRP, VEGFR3, RANTES, Pentraxin3, Ferritin, CCL18, MPO, GDF-15, MMP-1, PDGF-BB, Procalcitonin, MDC, Myoglobin, and VCAM-1." (PMID 33732236, 2021).
rectal cancer (1 paper, 2024). A primary or metastatic malignant neoplasm that affects the rectum. "We identified 15 proteins associated with colorectal, colon, and/or rectal cancer, such as AREG and GDF15 [1.30 (1.19–1.42) and 1.32 (1.20–1.45)]." (PMID 38750076, 2024).
retinal degeneration (1 paper, 2024). Degeneration of the retina. "Therefore, while GDF15’s association with retinal degeneration varies, fully understanding its role in neuroretina inflammation requires further evidence and additional timepoints." (PMID 39737171, 2024).
retinal detachment (1 paper, 2024). An eye emergency condition which may lead to blindness if left untreated. "Following retinal detachment, GDF-15 induces apoptosis by activating caspase-3." (PMID 38397833, 2024).
retroperitoneal fibrosis (1 paper, 2018). "The presence of retroperitoneal fibrosis (odds ratio (OR) 3.47, 95% confidence interval (CI) 1.2–11.4, P = 0.026) and the presence of parotid gland involvement (OR 3.92, 95% CI 1.0–19.5, P = 0.048) were independently associated with high GDF-15." (PMID 30547825, 2018).
rhabdomyolysis (1 paper, 2025). Necrosis or disintegration of skeletal muscle often followed by myoglobinuria. "This approach integrates circulating concentrations of GDF-15 and creatine kinase with cases of rhabdomyolysis caused by trauma." (PMID 40731746, 2025). "The model integrates serum levels of growth differentiation factor-15 (GDF-15), creatine kinase (CK), and occurrence of rhabdomyolysis associated with trauma." (PMID 40731746, 2025). "When categorized by the etiology of rhabdomyolysis, GDF-15 levels were significantly higher in the trauma group (median: 5741.50 pg/mL, IQR: 2830.50) than in the excessive exercise group (median: 2958.50 pg/mL, IQR: 1386.00; p = 0.001)." (PMID 40731746, 2025). "Moreover, individuals diagnosed with rhabdomyolysis had significantly higher GDF-15 levels (median: 3580.50 pg/mL, IQR: 3108.50) compared to healthy controls (median: 2378.00 pg/mL, IQR: 1314.00; p = 0.001)." (PMID 40731746, 2025). "Therefore, evaluating GDF-15 together with CPK, which is more specifically associated with rhabdomyolysis, increases diagnostic and prognostic accuracy; it provides stronger and more reliable results, especially in determining the risk of renal damage." (PMID 40731746, 2025). "The basic parameters used in creating the scoring system are CK levels above 50,000 U/L, GDF-15 levels within the specified threshold values (between 3500 and 5000 pg/mL and above 5000 pg/mL), and whether rhabdomyolysis developed due to trauma." (PMID 40731746, 2025). "However, there is no study in the literature regarding the use of GDF-15 for diagnostic or prognostic purposes specifically for rhabdomyolysis." (PMID 40731746, 2025). "We hypothesized that combining GDF-15 levels with CK measurements and trauma etiology would enhance the predictive accuracy for AKI in patients with rhabdomyolysis." (PMID 40731746, 2025).
serous ovarian adenocarcinoma (1 paper, 2018). "Further study showed that the pathological types of CA125 negative patients were mostly non-serous ovarian adenocarcinoma, indicating GDF15 could complement the application of CA125 in those non-serous pathological types." (PMID 29580231, 2018).
serous ovarian carcinoma (1 paper, 2020). "Because low-grade serous ovarian carcinoma is relatively resistant to chemotherapy, developing GDF15 as a potential serum biomarker to select patients that are sensitive to chemotherapy warrants further investigation." (PMID 33086658, 2020).
skin aging (1 paper, 2024). The gradual irreversible changes in structure of skin that occur as a result of the passage of time.. "Verification of these mechanisms will enhance our understanding of the intricate interplay between GDF15 and the molecular pathways implicated in light radiation-induced skin aging." (PMID 38195709, 2024).
spinal cord ischemia (1 paper, 2016). Reduced blood flow to the spinal cord which is supplied by the anterior spinal artery and the paired posterior spinal arteries. "Hence, GDF15 may be secreted from CD34-positive cells that have been mobilized in peripheral blood following IPC, explaining the protective effects against spinal cord ischemia." (PMID 27905554, 2016).
spondylitis (1 paper, 2022). The inflammation of a vertebra. "Bath Ankylosing Spondylitis Functional Index scores, disease duration, and age were significantly positively correlated with GDF-15 levels." (PMID 36104054, 2022). "In addition, GDF-15 was positively correlated with age, Bath Ankylosing Spondylitis Functional Index score, and disease duration." (PMID 36104054, 2022). "Bath Ankylosing Spondylitis Functional Index has a stronger correlation with disease duration than BASDAI.Therefore, the correlation between GDF-15 and BASFI in the current study may be related to the correlation between GDF-15 and disease duration." (PMID 36104054, 2022).
synucleinopathy (1 paper, 2024). A neurodegenerative disease that is characterized by the abnormal accumulation of aggregates of alpha-synuclein protein in neurons, nerve fibers or glial cells. "Furthermore, elevated serum GDF15 was associated with disease duration and worsened motor and cognitive scores and was reflective of poorer neurological outcomes in these synucleinopathy cohorts." (PMID 39737171, 2024). "A sex effect was also uncovered, with higher serum GDF15 in male synucleinopathy patients relative to females." (PMID 39737171, 2024). "Thus, there is some support for increased serum GDF15 in synucleinopathy, and this elevation may be an intrinsic component of synuclein pathogenesis." (PMID 39737171, 2024).
systemic inflammatory response syndrome (1 paper, 2024). SIRS is a serious condition related to systemic inflammation, organ dysfunction, and organ failure. "We investigated whether GDF15 correlates with the postoperative systemic inflammatory response syndrome (SIRS) typically observed after CPB by assessing the association between GDF15 levels and CPB and aortic-cross clamp times." (PMID 39766300, 2024).
thalassemia intermedia (1 paper, 2012). "Interestingly, GDF15 expression was upregulated, which also has been observed in thalassemia intermedia, and associated with repression of hepcidin, an important mediator of the inflammatory response on erythropoiesis." (PMID 22747986, 2012).
Thrombocytopenia (1 paper, 2021). A reduction in the number of circulating thrombocytes. "The link of circulating GDF-15 as an early predictive marker of delayed thrombocytopenia related to CGM097 or other HDM2 inhibitors would require further investigations beyond the exploratory analysis of this study." (PMID 34140638, 2021). "Overall, this work provides an integrated quantitative understanding of thrombocytopenia and the GDF-15 biomarker changes in response to HDM2 inhibitors, with potential use in dosing regimen optimisation and patient benefit." (PMID 34140638, 2021). "The PK/PD model-derived individual drug potency on GDF-15 production on day 1 was associated with the drug thrombocytopenia potency, raising the possibility to use GDF-15 induction as a prospective marker in the identification of patients at a higher risk of developing delayed thrombocytopenia." (PMID 34140638, 2021). "PK/PD models well described the time course of platelet and serum GDF-15 changes, providing a tool to predict response to CGM097 for dose-limiting thrombocytopenia and GDF-15 biomarker." (PMID 34140638, 2021).
tongue squamous cell carcinoma (1 paper, 2025). A squamous cell carcinoma that arises from the tongue. "Among these genes, GDF15 has been confirmed to play a metastasis‐promoting role in most studies, whereas ZMIZ1 has been found to affect invasion and metastasis in tongue squamous cell carcinoma (TSCC)." (PMID 39817582, 2025).
unstable angina pectoris (1 paper, 2024). "GDF-15 is emerging as a prognostic factor in ACS patients and is associated with NSTEMI, unstable angina pectoris, and STEMI, which are the causes of the erosion or rupture of vulnerable atherosclerotic plaques resulting in AMI or death." (PMID 39193498, 2024).